RUNX3 (RUNX family transcription factor 3)
Diseases named in the same sentence as RUNX3 in open-access papers (continued):
Sharing a sentence is not in itself a finding about the gene and the disease.
tumor (continued). "Many studies have indicated that the overexpression of DNMT1 could silence vital tumor suppressor genes such as APC, P16, and RUNX3 through DNA methylation." (PMID 28473984, 2017). "Considering Gronerʼ results, RUNX3 is not expressed frequently in epithelial cells and hence, we cannot anticipate a tumor suppressor role for RUNX3 in these cell lines." (PMID 29201108, 2017). "On the other hand, SMAD4 haploinsufficient KPDC mice (SMAD4(+/−)) lacked RUNX3 expression, had a significantly lower metastatic burden, but showed an increased proliferative activity of the primary tumor compared to KPC tumors." (PMID 29100342, 2017). "To compare the CIMP classifications derived from our clustering analysis to those derived from the Weisenberger panel of genes, we analysed the methylation status of our tumour samples using MethyLight at each gene from this panel (CACNA1G, NEUROG1, SOCS1, IGF2, RUNX3)." (PMID 28351398, 2017). "In contrast, some loci have been found hypermethylated with age (e.g., estrogen receptor, interferon γ, insulin-like growth factor II, promoters of tumor-suppressor genes such as lysyl oxidase (LOX), p16INK4a, runt-related transcription factor 3 (RUNX3), and TPA-inducible gene 1 (TIG1))." (PMID 26703582, 2015). "Since RUNX3 did not affect tumor cell proliferation in vitro, it is likely that RUNX3 suppressed tumorigenesis in vivo through blocking VEGF in endothelial cells (angiogenesis)." (PMID 24475196, 2014). "As expected, the Runx genes (Runx2 and Runx3) and Myc family targets (Myc, Mycn) conformed to this pattern, being selected in CD2-MYC and CD2-Runx2 respectively and effectively disappearing from the double transgenic tumours." (PMID 24586197, 2014). "In all, 29/55 samples showed the same trend of decreased RUNX3 and miR-30a expression in tumour rather than normal tissue." (PMID 24447545, 2014). "Statistical analysis showed that the expression of RUNX3 in tumour tissue was significantly lower than that in surrounding normal mucosa." (PMID 24447545, 2014). "To determine how RUNX3 inhibits RCC cell migration and invasion, we focused on elucidating the relationship between RUNX3 and MMPs which has been reported to participate closely in tumor progression." (PMID 23457532, 2013). "Other factors, such as tumor invasion of blood vessels, lymph nodes or lymphatic ducts, and tumor metastases, also demonstrated no relation with RUNX3 methylation." (PMID 21867527, 2011). "In the remaining three pairs, a weak RUNX3 expression signal was detected in the tumor-free resection margins; thus, no negative RUNX3 signal was detected in the tumor-free resection margins." (PMID 21205319, 2011). "Notably, four of these TFs—RUNX3, GABPB1, GABPA, and BCL6B—are known tumor suppressors." (PMID 40432923, 2025). "The pathway is normally restrained by tumor suppressors including chromosome 8 open reading frame 4 (C8orf4)—which binds the NOTCH2 intracellular domain (N2ICD) to prevent nuclear translocation —and runt-related transcription factor 3 (RUNX3), which suppresses Jagged1-NOTCH signaling." (PMID 41438763, 2025). "Therefore, while RUNX3 KO did not significantly affect primary tumor growth, it significantly reduced metastatic outgrowth." (PMID 38240752, 2024). "RUNX3-overexpression synergises with inhibition of protein kinase B (Akt) to promote additional TCM differentiation in CAR-T cells, which produces robust and improved anti-tumour responses in pancreatic ductal adenocarcinoma patient-derived xenograft tumour models." (PMID 39399500, 2024). "In the tumor tissue derived from A549 and H2199 NSCLC cells, protein levels of RUNX3 were increased when MEX3C was inhibited but Suv39H1 protein levels were lower, indicating that RUNX3 could negatively control Suv39H1." (PMID 38424632, 2024). "As expected, the tumor cells typically showed weak or no RUNX3 protein staining." (PMID 37400551, 2023). "Normal expression of RUNX3 in H520 cells did not function as a tumor suppressor in this study." (PMID 37438719, 2023).
tumor (continued). "Anada and Matthewd’s research showed that the expression of Runx-3 promoted the formation of tissue-resident memory T cells, and they use melanin model revealed that the metastasis and localization of CD8+ T with high expression of Runx-3 in TME inhibited the growth of tumor." (PMID 36969190, 2023). "The fact that RUNX3 has the ability to regulate MYC at two different levels – through attenuation of Wnt signaling and MYC protein destabilization – may explain why RUNX3 functions as a potent tumor suppressor in the intestine and lung." (PMID 37400551, 2023). "Conversely, when stromal RUNX3 expression is weak or negative, tumor proliferation may be slower but metastasis may occur more frequently." (PMID 37641472, 2023). "We also drew survival curves based on the Runx3 levels in T cells, not in tumor cells." (PMID 37189103, 2023). "Furthermore, RUNX3 is an important mediator during the development of both CD4+ and CD8+ cytotoxic T-lymphocytes (CTL), and is thus likely pivotal in the development of anti-tumor immunity." (PMID 36900240, 2023). "However, the precise molecular mechanism of RUNX3 methylation by G9a under hypoxia and its links to tumor suppressive functions of RUNX3 were not fully investigated." (PMID 33116296, 2021). "RUNX3 was weakly positive in tumor tissue but negative in normal tissue." (PMID 33401247, 2020). "Also, it remains an open question whether cytoplasmic RUNX3 holds some oncogenic effects, since to date no publication refers to the possible pro‐tumour role of cytoplasmic RUNX3, independent of the loss of its tumour‐suppressor effects due to nuclear dislocation." (PMID 32307917, 2020). "Its tumor suppressive activity was first identified in gastric epithelial cells of RUNX3 knockdown mice, where absence of RUNX3 resulted in increased proliferative activity, suppressed apoptosis and decreased sensitivity to transforming growth factor beta (TGF-β)." (PMID 33298014, 2020). "In addition, RUNX3 is involved in the regulation of epithelial-mesenchymal transition (EMT) by directly regulating the transcription of blocking protein-1, thus inhibiting tumor invasion and metastasis by protecting nesting apoptosis." (PMID 32184893, 2020). "For instance, the high expression of RUNX3 could inhibit tumor microvascular generation in order to exhibit negative control response on invasion and distant metastasis in colorectal adenocarcinoma." (PMID 29651226, 2018). "Thus, we speculated that miR-544 was closely related with RUNX3 and NCR1 expression in tumor immune escape." (PMID 29636640, 2018). "But DAPK promoter methylation had a similar frequency in the blood in GC and controls, these results suggested that promoter methylation of the ten tumor-related genes (p16, CDH1, RUNX3, MLH1, RASSF1A, p15, APC, GSTP1, Reprimo, and MGMT) may be potential biomarkers based-blood test for GC." (PMID 29100425, 2017). "However, we observed no obvious correlations between RUNX3 and patient gender, age, tumor volume, or grade." (PMID 28977878, 2017). "Therefore, an integrated analysis was performed to evaluate the ability of 11 tumor-related genes (p16, CDH1, RUNX3, MLH1, RASSF1A, p15, APC, DAPK, GSTP1, Reprimo, and MGMT) promoter methylation test using blood samples as a feasible biomarker in GC diagnosis and screening." (PMID 29100425, 2017). "All these information tempted us to check whether RUNX3 has any role in the transcriptional activation of FOXP3 in tumor-induced CD8+ Treg cells or not." (PMID 28487507, 2017). "After adjusting for sex and age, RUNX3-/SMAD4+ status remained a significant independent predictive factor for favorable overall [p = 0.025, HR 1.842 (95% CI 1.079–3.143)] and progression-free survival [p = 0.020, HR 1.850 (95% CI 1.100–3.113)] on multivariate analysis, in addition to tumor size." (PMID 29100342, 2017).
tumor (continued). "To determine whether RUNX3 promotes KGN tumor formation in a mouse xenograft model, we subcutaneously injected KGN/Vector and KGN/RUNX3 cells into contralateral flanks of female NSG (NOD-scid IL2R-gammanull) mice and monitored tumor formation twice a week by palpation for up to 185 days." (PMID 31311113, 2019). "However, RUNX3 was not added into the DEABM based on its known tumor suppressor capability, rather it was chosen for its effect on suppressing the proliferative potential of ER+ cells, a functional capability that needed to be added to the earlier version of the DEABM." (PMID 23704974, 2013). "In a mouse model of ACT for melanoma, CD8+ TILs lacking Runx3 (key regulatory factors of TRM cells) expression did not accumulate within tumors, leading to increased tumor growth and heightened mortality rates." (PMID 39802636, 2025). "The adoptively transfer of CD8+T cells lacking Runx3, which is vital for the differentiation of CD8+TRM cells, leads to insufficient infiltration of CD8+ T cells into tumors and inadequate control of tumor growth." (PMID 40066223, 2025). "It was also found to reduce cytokine release in in vitro experiments, and CAR-T cells that overexpress RUNX3 are safer than conventional CAR-T cells and show no reductions in their anti-tumor effects." (PMID 38919533, 2024). "Inversely, the mRNA expression of RUNX3 in LUAD tissues decreased with tumor grade and a significantly negative correlation was obtained by Pearson analysis between the mRNA expression of MEX3C and RUNX3 (P < 0.0001, r = − 0.6151)." (PMID 38424632, 2024). "In a preclinical model of melanoma, adoptive transfer of CD8+ TIL lacking expression of Runx3 and which did not exhibit a TRM cell phenotype resulted in uncontrolled tumor growth and low animal survival." (PMID 30180905, 2018). "Twenty eight (~90%) of these pairs showed a negative or weak signal for RUNX3 expression in HCC tissue, but showed RUNX3 protein expression in tumor-free resection margins." (PMID 21205319, 2011). "Interestingly, preserved SMAD4 or RUNX3 resulted in similar 5-year DSSs in the tumor epithelial compartment ( 70%), but not in the stromal compartment (SMAD4-/RUNX3+ 80%, SMAD4+/RUNX3- 60%)." (PMID 36900240, 2023). "The frequency of the methylation in tumour tissue was 57.1% in p16, 2.4% in DAP-kinase, 23.8% in GSTP1, 90.5% in APC, 45.2% in RIZ1, 64.3% in SFRP1, 59.5% in SFRP2, 28.6% in SFRP5, 47.6% in RUNX3, and 54.8% in SOCS1, while in MGMT, no aberrant methylation was detected." (PMID 17968429, 2007). "Nonetheless, one probe (cg00117172) mapped in the nonpromoter region of RUNX3 (body gene) was hypermethylated in both comparisons, PDTC/ATC vs NT (Δβ = 0.313) and WDTC-PP vs WDTC-GP (Δβ = 0.102), reinforcing their potential as biomarkers of tumor aggressiveness." (PMID 28938489, 2017).
cancer (227 papers, 2004 to 2026). A tumor composed of atypical neoplastic, often pleomorphic cells that invade other tissues. "RUNX3 inactivation, as found in this study, has been associated with the progression of several cancers including NSCLC." (PMID 38424632, 2024). "RUNX3 has been linked to the development of cancers such as colorectal cancer, liver cancer, lung cancer, and breast cancer." (PMID 38424632, 2024). "The RUNX family, consisting of RUNX1, RUNX2, and RUNX3, has been recognized as crucial regulators in developmental processes, with dysregulation of these genes also being implicated in tumorigenesis and cancer progression." (PMID 39822248, 2024). "Runt domain transcription factor 3 (RUNX3) suppresses many different cancer types and is disabled by mutations, epigenetic repression, or cytoplasmic mislocalization." (PMID 38683453, 2024). "Re-expression of RUNX3 (activation) induced anti-cancer effects and regulated susceptibility to cetuximab and 47Sc-conjugated cetuximab, highlighting the key role of RUNX3 in these processes." (PMID 37438719, 2023). "We also confirmed that the Frt-Stop-Frt cassette was deleted from the Runx3FSF allele in the KPRL/F-TAM(+) cancers, indicating that Runx3 was restored in these cancers." (PMID 37887282, 2023). "Unlike RUNX1, which is frequently mutated in human cancer, the RUNX3 gene is often transcriptionally silenced in cancer by CpG island DNA methylation or through EZH2-dependent H3K27me3 (histone H3 lysine 27 trimethylation) modification in the RUNX3 promoter." (PMID 37190015, 2023). "A recent study using cancer-derived RUNX3 mutation R122C revealed a gatekeeper role for RUNX3 in gastric epithelial stem cell homeostasis." (PMID 36766749, 2023). "In this respect, it has been well established that RUNX3 is silenced in various cancers, and that its silencing is caused by promoter DNA hypermethylation." (PMID 36231060, 2022). "Loss of the chromosomal region (1p36), where RUNX3 is located, is frequently found in various cancers, such as breast, liver, lung, bowel, nerve, and pancreatic cancers." (PMID 36429115, 2022). "Loss of expression and cytoplasmic mislocalization had been indicated partly as underlying causes of RUNX3 dysfunction in many cancer types." (PMID 35368900, 2022). "Another regulatory factor implicated in several carcinomas is RUNX3 (runt related transcription factor 3), which belongs to a family of transcription factors that modulate major developmental pathways." (PMID 35159060, 2022). "Methylation of this tumor suppressor RUNX3 has been negatively associated with overall survival in other carcinomas." (PMID 35159060, 2022). "In-Patient 1, variants in FNIP1, PPP1R15A, WDR19, and RUNX3 were present in ~100% of cancer cells across all samples." (PMID 34400647, 2021). "Using somatic mutations of RUNX3 from Catalog of Somatic Mutations in Cancer (COSMIC) database and TCGA data portal, two mutation cluster regions (MCR1 and 2) near K129 and K171 were identified." (PMID 33116296, 2021). "Recently, additional roles of Runx3 in metastasis have been implicated in processes such as regulation of the cancer microenvironment, angiogenesis, stemness, immunosurveillance, and inflammation." (PMID 33672337, 2021). "Further investigations in vivo, also in different cancer contexts, must be carried out to fully understand the dichotomy of RUNX3 transcript variants." (PMID 33530588, 2021). "EZH2 is frequently over-expressed in a variety of cancers and its over-expression has been implicated in the down-regulation of RUNX3." (PMID 32943993, 2020). "The oncogenic activity of NF-κB is enhanced by the action of RUNX3 TV1 encoded isoforms while TV2 impacts its cancer inhibitory function." (PMID 29342962, 2018).
cancer (continued). "Many genes, such as Bcl-xl, kRAS, COX, iNOS, APC, Smad3, STAT3, Ptgs2, Tnfrsf6, p16, Mlh1, Runx3, Dapk, and β-catenin are mutated in stages of carcinogenesis of the UC-associated cancer." (PMID 28621756, 2017). "The sensitivity to TGF- β was re-established in RUNX3-deficient cancer cells after reintroducing RUNX3 into those cells which showed increased expression of proapoptotic gene BIM." (PMID 27825140, 2017). "Transcriptional silencing of RUNX3 by hypermethylation was associated with various human cancers, including NSCLC." (PMID 26862903, 2016). "Further, RUNX3 was reported to control Notch signaling which is tightly linked to cancer stem cell (CSCs)." (PMID 25229459, 2014). "The chromosomal locus for RUNX3 (1p36) shows frequent loss of heterozygosity in a variety of cancer types including colon and gastric carcinomas." (PMID 19223906, 2009). "Reduced expression of RUNX3 was frequently caused by CpG island hypermethylation in various types of cancer." (PMID 19521519, 2009). "In certain type of human cancers including gastric and bladder, it has been reported that point mutations of RUNX3 were observed." (PMID 19521519, 2009). "Although rare, RUNX3 missense mutations have been identified in cancer patients." (PMID 36766749, 2023). "Notably, Runx3-deficient mouse models are cancer prone in different tissue types, such as the intestine, mammary gland, stomach and lung." (PMID 36766749, 2023). "Runx3-deficient mice are predisposed to cancers of the breast, lung, and gastrointestinal tract." (PMID 36766749, 2023). "Somatic mutations in RUNX2 and RUNX3 are rare in different cancers." (PMID 36429115, 2022). "In addition, hypermethylation of RUNX3 promoter has been associated with down-regulation of RUNX3 gene expression in cancers." (PMID 32943993, 2020). "In addition, mutations in RUNX3 have been shown in gastric and bladder cancers." (PMID 19223906, 2009). "The presence of RUNX3 CpG island hypermethylation in GCTs, but not in normal ovarian tissue or peripheral blood suggests that RUNX3 hypermethylation might be associated with the genesis of this cancer type and this frequent methylation might serve as a biological marker." (PMID 15574200, 2004). "Former studies have highlighted RUNX3 as a prognostic factor across several cancer types, but few have studied its cell-type specific expression patterns." (PMID 41644763, 2026). "Ro/e also indicated RUNX3_Neg cancer tissues were more prone to macrophage depletion, while RUNX3_Pos tissues were more prone to macrophage enrichment." (PMID 40916017, 2025). "On the contrary, RUNX3_Neg cancer tissues are more prone to monocyte enrichment, while RUNX3_Pos tissues are more prone to monocyte depletion." (PMID 40916017, 2025). "MEX3C mRNA levels were higher in LUAD cancer tissues than in normal paraneoplastic tissues, while RUNX3 expression trended in the opposite direction." (PMID 38424632, 2024). "In contrast, RUNX3 was more frequently downregulated in several cancer types, including BLCA, COAD, LIHC, LUAD, THCA, and THYM." (PMID 39822248, 2024). "In contrast, RUNX3 was identified as a super-enhancer-associated oncogene in AML and was one of the most highly expressed genes in this cancer type." (PMID 37190015, 2023). "RUNX3 is frequently inactivated in human cancer cell lines and cancer samples through hemizygous deletion, promoter hypermethylation, histone modification, and protein mislocalization." (PMID 37438719, 2023). "The therapeutic effect of 47Sc-DTPA-cetuximab on cancer cell growth was effectively enhanced by RUNX3 expression." (PMID 37438719, 2023).